STAT3 (signal transducer and activator of transcription 3)
Diseases named in the same sentence as STAT3 in open-access papers (continued):
Sharing a sentence is not in itself a finding about the gene and the disease.
tumor (continued). "Curcumin was further investigated for its potent role in reducing CAF (cancer-associated fibroblast)-induced resistance to 5-FU in tumor cells through the suppression of the JAK/STAT3 signaling pathway." (PMID 36015440, 2022). "Activation of STAT3 in the tumor causes transfer of indicators from the different growth factors and cytokines which in turn induces certain target genes such as Cyclin-D, c-Myc, and CDC25A." (PMID 36359888, 2022). "EGFR mutations cause abnormal activation of the downstream JAK/STAT3 signalling pathway, leading to the expression of increased phosphorylated STAT3, and hence abnormal tumor proliferation, angiogenesis, invasion, and metastasis." (PMID 36185620, 2022). "Numerous point mutations in the STAT3 protein have been identified that drive malignancy in various tumor entities." (PMID 35752777, 2022). "Further research on cell lines showed that knockdown and inhibition of STAT3 attenuates the proliferation, migration and invasion of tumor cells caused by overexpression of SHC4." (PMID 35033067, 2022). "The mechanisms that underlie CRT-resistance, both tumor-intrinsic as well as tumor-extrinsic ones, are actively debated including the functional role of STAT3." (PMID 33530306, 2021). "For the complexity of the mutation variation and compensative access in tumor, the tumor type specificity including the mutation landscape has become a primary concern before the utilization of STAT3 inhibitors." (PMID 34502195, 2021). "The persistent activation of STAT3 is attributed to the disruption of negative modulators of STAT3 signaling, somatic mutations in STAT3, enhanced activity of upstream kinases, and establishment of the positive feedback loop in the tumor microenvironment." (PMID 35053027, 2021). "The feedback activation of STAT3 by PI3K/mTOR inhibitors raises the possibility that simultaneously targeting PI3K/mTOR and STAT3 activity in PTEN-deficient cancer cells can synergistically inhibit tumor progression." (PMID 33431808, 2021). "For example, interleukin‐2‐mediated STAT3 activity expands tumour‐associated regulatory T cells and enhances Foxp3 expression in CD4+ T cells." (PMID 34449972, 2021). "After these recruited and amplified MDSCs further infiltrate tumor tissues and enter the deep vascular deficiency region, hypoxia-driven mechanism takes the lead to down-regulate STAT3 and promote the differentiation of MDSCs to TAMs." (PMID 34625124, 2021). "Numerous studies have highlighted a role for STAT3 as a negative regulator of NK cell activity, since loss of STAT3 in NK cells enhances NK cell-dependent tumor surveillance across different cancer types." (PMID 34944848, 2021). "Contrary to that, loss of STAT3 in PTEN-deficient mice enhanced tumor growth and metastasis, suggesting that STAT3 suppresses oncogenic progression in PTEN -deficient PCa." (PMID 34638338, 2021). "Several studies have demonstrated increased ROS in tumor cells following loss of STAT3, and this effect has been shown to be mediated, at least in part, by mitochondrial STAT3, which regulates the activity of complex I." (PMID 33605027, 2021). "The activation abnormalities in the signal transducer and activator of transcription 3 (STAT3) signaling pathway are associated with tumor onset and progression." (PMID 34365903, 2021). "In the nucleus, the JAK/STAT3 signaling pathway is continuously activated to cause uncontrolled tumor cell proliferation, resist apoptosis, support angiogenesis, and evade immune surveillance." (PMID 34567204, 2021). "These factors are also involved in the Jak-STAT3 signaling pathway in the chronic inflammation-associated tumor growth and immunosuppressive process." (PMID 34379689, 2021). "STAT3 induces various gene sets associated with tumor progression, many of which are common targets of NF-κB." (PMID 34063828, 2021).
tumor (continued). "(A–C) Box plots of MYC (A), NFKB1 (B), and STAT3 (C) expression in tumor-associated stroma from the GSE14548 dataset by disease grade (grade 1: G1; grade 2: G2; grade 3: G3)." (PMID 34169837, 2021). "These activate STAT-3 and NF-kB, both of which are implicated in several cellular signaling pathways involved in inflammation, apoptosis, cell proliferation, and tumor development." (PMID 34064419, 2021). "Recent evidence reveals that STAT3 binds to the PD-L1 promoter and induces PD-L1 transcription activation to regulate tumor cells and the tumor-associated immune environment." (PMID 34440920, 2021). "So, finding the balance between the pros and cons of targeting HIF-1α and STAT3 can be a direction to solve the problems associated with tumor therapy through modulating the immune response." (PMID 34692527, 2021). "The importance of STAT3 activation was emphasized by Pawlus and his colleagues in a previous report, where STAT3 knockdown in tumor cells caused inhibition of proliferation, mimicking the phenotype displayed by NK cells after HIF-1α knockdown under hypoxia." (PMID 33920906, 2021). "NF-κB and STAT3 interact in several different ways to boost tumor-associated inflammation and consequently suppress antitumor immune responses." (PMID 34440829, 2021). "Signal transducers and activators of transcription 3 (STAT3) has been implicated as an oncogene and therapeutic target in a variety of neoplastic diseases including OS." (PMID 34309110, 2021). "Previous studies have showed that the inhibition of STAT3 signaling pathways will lead to tumor-associated G2/M phase arrest." (PMID 34760885, 2021). "STAT3/HIF-1a axis plays a crucial role in adapting tumor cells to the hypoxic environment associated with cancer progression." (PMID 33672756, 2021). "CPEB3 can disrupt the crosstalk between cancer cells and tumor-associated macrophages through the IL-6R/STAT3 signaling pathway, and thereby inhibit epithelial-mesenchymal transition." (PMID 34879089, 2021). "In aggressive metastatic ovarian carcinoma, tumor-associated macrophages (TAMs) are involved in the secretion of IL-6 which induces EMT via activation of STAT3." (PMID 34220337, 2021). "IL-6 and STAT3 in TME are linked with angiogenesis that is the step for tumor migration and metastasis." (PMID 34112144, 2021). "While being highly activated in both tumor-associated immune cells and tumor cells, STAT3 plays crucial roles in downregulating anti-tumor responses to promote tumorigenesis." (PMID 33925645, 2021). "Aberrant STAT3 expression and activation (through phosphorylation) is observed in various solid and hematological tumors, and is associated with tumor growth and progression." (PMID 33668421, 2021). "STAT3 signalling has a close association with inflammation which is subsequently linked with tumour initiation and tumorigenesis." (PMID 34078370, 2021). "IL-6 was found to be secreted by tumor-associated fibroblasts, and conditioned media from fibroblasts activated STAT3 in NPC cells." (PMID 34885950, 2021). "Activation of STAT3 stimulates tumour-associated angiogenesis via modulating the stability and activity of hypoxia-inducible factor-1α (HIF-1α) as well as enhancing VEGF expression by binding to the VEGF promoter with HIF-1α." (PMID 34298667, 2021). "TYK2 deficiency reduces MPNST tumor growth through decreased proliferation and increased apoptosis mediated via lower phosphorylated STAT3 (p-STAT3) and BCL-2 with a concomitant increase in caspase 3 cleavage." (PMID 34439323, 2021). "VEGF, IL-6 and IL-10, which are usually overexpressed in TME, can activate STAT3 signaling, thereby inducing an immature tolerance phenotype in tumor-associated DCs and promoting tumor progression." (PMID 33935714, 2021).
tumor (continued). "On the other hand, in a murine chemical carcinogenesis model, Stat3-deficient keratinocytes go to apoptosis after DMBA-treatment and tumor formation is completely prevented in Stat3-deficient mice after DMBA/TPA-treatment." (PMID 34572732, 2021). "Chemotherapy activated the EZH2/STAT3 pathway in tumor cells, which caused an increase in miR-378a-3p and miR-378d levels in cells and exosomes." (PMID 33823894, 2021). "In a cancerous tumor, cytokines, such as IL10, secreted by the cancer cells, and the transcription factor STAT-3, cause induction of the competing enzyme arginase-1 (Arg1) in the tumor-associated microglia and macrophages (TAM)." (PMID 34575998, 2021). "Using protein lysates obtained from the xenografted tumor tissues, treatment with flubendazole caused a decrease in the levels of p-STAT3 and induced the expression of apoptosis protein of BAX; meanwhile, the BCL2 level was reduced." (PMID 34513827, 2021). "We further observed that tumor malignancy was significantly lower in patients with mutations in the DNA-binding domain of STAT3 compared to those with the mutations in the SH2 domain (χ2=12.346, p=0.011) and the N- or C-terminal regions (χ2=5.611, p=0.027)." (PMID 33535185, 2021). "This STAT3 dimer stimulates the transcription of genes strongly associated with the promotion of tumor growth and immunosuppression." (PMID 34367982, 2021). "Activation of STAT3 is closely related to tumorigenesis, and STAT3 can cause tumor cell proliferation and migration." (PMID 34149924, 2021). "GMME1 specifically blocked CCR2‐associated STAT3 phosphorylation and induced tumour cell apoptosis, thereby inhibiting tumour proliferation." (PMID 34464477, 2021). "Inflammatory COX‐2/STAT3 signalling is upregulated by tumour‐associated macrophages (TAMs) and promotes OS cell migration, invasion, and EMT in mouse and OS patients." (PMID 33382511, 2021). "In the context of cancer, STAT1 is considered a tumor suppressor while STAT3 is often associated with tumor progression." (PMID 33526787, 2021). "Persistently activated STAT3 in tumor-associated B cells, CD4+ and CD8+ T cells upregulates expression of immunosuppressive factors while inhibiting immuno-stimulating molecules." (PMID 34956861, 2021). "As a tumour growth promoter, NF-κB has been found to induce expression of oncogenic microRNAs, promote expression of immune checkpoint proteins like PD-L1 and also act in sync with STAT3 and AP-1 to induce tumour-associated inflammation." (PMID 34867402, 2021). "Studies with murine cancer models and genetic deficiencies in IL-6 or STAT3 have substantiated their role in several different tumor types." (PMID 33651821, 2021). "Other cell population like tumor associated fibroblasts can secrete proinflammatory factors like IL-6, which activates STAT3, and secrete CXCL12 that inhibit T-cells infiltration in tumors." (PMID 33477288, 2021). "Seven studies (9 trials) investigated the association between STAT3/p-STAT3 expression level and tumour grade (G1 + G2 vs. G3), with a combined total of 953 patients." (PMID 34789292, 2021). "IL6 can also induce pro-angiogenic effects, inducing VEGF expression in tumour-associated endothelial cells through STAT3 and MAPK, while the IL6 inflammatory loop can activate mechanisms linked to drug resistance." (PMID 34834425, 2021). "In the context of cancer disease, PTPRD is absent or inactive in a variety of human tumor types, playing a tumor suppressor role linked with the downregulation of STAT3 activity." (PMID 34957126, 2021). "Signal transducer and activator of transcription protein 3 (STAT3) is a transcription factor associated with the occurrence, invasion, and metastasis of tumours." (PMID 34225581, 2021). "Specifically, tumor-infiltrating and tumor-associated NK cells from STAT3-deficient tumor-bearing mice express enhanced levels of NKG2D, CD69, FASL, granzyme B, perforin, and IFN-γ, reducing tumor growth and improving survival." (PMID 34025641, 2021).
tumor (continued). "Taken together, our results suggest that STAT3 mutations in the DNA-binding domain are tumor suppressive." (PMID 33535185, 2021). "Several studies have shown that tumours with STAT3 activation become more aggressive and are associated with poor prognosis in HCC patients." (PMID 33410581, 2021). "STAT3 is hyperactivated in tumors and associated with less matured tumor-associated DCs, which results in a poor response to TLR stimulation and subsequent poor clinical prognosis." (PMID 33668746, 2021). "In the tumor microenvironment, it is well established that Stat3 activation in TAM skewing to M2 phenotype is associated with malignant behavior in various cancers." (PMID 34178651, 2021). "In contrast, STAT3 is widely associated with immunosuppression, cancer cell survival, and persistent inflammation in the tumor microenvironment." (PMID 34852825, 2021). "It has been extensively documented that STAT3 is also persistently activated in tumor-associated immune cells." (PMID 33491667, 2021). "It has been suggested that STAT3 is a direct transcriptional regulator of ATX and that downregulation of STAT3 causes a significant reduction in ATX protein expression in human tumor cells." (PMID 34140021, 2021). "These factors, along with IL-2, subsequently activate STAT3 signaling in tumor associated-TRegs to promote their expansion." (PMID 34483843, 2021). "STAT3 is constitutively activated in many different types of cancers and tumor-infiltrating immune cells and has been associated with a poor prognosis." (PMID 34684783, 2021). "Stress and inflammation can trigger and/or sustain STAT3 activity in PC cells and, especially, in tumor-associated myeloid cells." (PMID 34830209, 2021). "Inhibition of STAT3 signaling in microglia is associated with a shift to an anti-tumor phenotype characterized by an increase in co-stimulatory molecule expression, decreased production of IL-10, and increased expression of pro-inflammatory cytokine TNF-α." (PMID 34483843, 2021). "Many tumor-promoting effects of IL-11, such as the promotion of cancer cell migration and invasion, have been linked to the STAT3 signaling cascade." (PMID 34917508, 2021). "To this end, we investigated associations of STAT3/CDK2/4/6 expressions with tumor-immune infiltration across the TCGA dataset." (PMID 33668805, 2021). "In concurrent studies at the time, STAT3 was implicated as a primary driver of tumor-mediated impairment of the immune system." (PMID 33919157, 2021). "TNFα, TGF-β, and STAT3 synergistically increased the risk of developing cancers and promoted tumor growth and cancer-associated cachexia." (PMID 34926700, 2021). "Stress and inflammation can trigger and/or sustain STAT3 activity in PCs, especially in immunosuppressive tumor-associated myeloid cells (macrophages, MDSCs)." (PMID 34945784, 2021). "STAT3 signaling of tumor cells interacted with the STING signaling-associated immune response, and these two signals played opposing effects in the tumor microenvironment." (PMID 34299262, 2021). "The activation of STAT3 in GBM-resident tumor-associated macrophages/microglia (TAMs) impaired their ability to mediate phagocytosis and led to their polarization toward an immunosuppressive phenotype." (PMID 34276757, 2021). "The proteins encoded by STAT3 target genes subsequently precipitated tumor proliferation (such as cyclin D1, BCL-xL)." (PMID 34712264, 2021). "In contrast to normal STAT3 activity, which is transient, constitutively active STAT3 is associated with abnormal cell growth and survival, angiogenesis and metastasis, tumor immune evasion, and aberrant mitochondrial function." (PMID 33718197, 2021). "The JAK2/STAT3 signaling pathway is associated with a malignant progression of tumor cells, such as cell proliferation, invasion, and immunoregulation." (PMID 33788424, 2021).
tumor (continued). "In vivo, targeting of the STAT3 signaling pathway in tumor-associated MDSCs leads to the elicitation of enhanced CD8+ T cell responses, activation of tumor-associated monocytes and DCs, and tumor regression." (PMID 33854974, 2021). "STAT3 is constitutively activated in approximately 50% of NSCLC primary tumours and NSCLC cell lines and is associated with poor prognosis." (PMID 34834295, 2021). "RON activation can cause the phosphorylation of STAT3, which is essential for the tumor‐promoting efficacies and immunosuppressive functions of TAMs." (PMID 33463063, 2021). "It thereby acts as a protein kinase and interacts with many tumor-associated genes to accelerate carcinogenesis including HIF1α, Oct-4, STAT3 and CTNNB1 that encode β-catenin." (PMID 33652661, 2021). "Tumor-associated macrophages (TAMs) promote tumor progression by secreting IL-6 to activate IL-6/STAT3 signals in adjacent HCC stem cells in liver tissue microenvironments." (PMID 34976809, 2021). "Abnormal activation of STAT3 in cancer is associated with the quantity and function of immunosuppressive tumor-promoting MDSCs." (PMID 33854974, 2021). "Recent research shows that regulatory mechanisms of CTC-mediated tumor metastasis involve Tumor-Associated Macrophages (TAMs) by regulating the JAK2/STAT3/miR-506-3p/FoxQ1 axis." (PMID 32429087, 2020). "In a preclinical model of HCC, miR-146a inhibition alters the STAT3 activation-associated cytokine profile improving the anti-tumor effect of lymphocytes." (PMID 32793185, 2020). "Numerus studies indicate that STAT3 is implicated in tumor cell proliferation, invasion, and metastasis in human cancers." (PMID 31949495, 2020). "Clinical studies in 724 patients with stage I–IV CRCs showed that STAT3 was significantly associated with poor outcomes and it supported the potential role of STAT3 in pro-tumor inflammatory transmission." (PMID 33505963, 2020). "Studies have shown that SHP‐2 protein deficiency can maintain tumor growth by promoting activation of the JAK/STAT3 pathway." (PMID 32875727, 2020). "Activated STAT3 predominantly detected in human cancers is constitutively activated and depicts its association with neoplasms." (PMID 32863742, 2020). "The receptor of IL-17 present on tumor and tumor-associated stromal cells can induce the IL-6 production when activated leading to activation of the oncogenic factor STAT3." (PMID 32121394, 2020). "The JAK2/STAT3 signaling pathway is an evolutionarily conserved signaling pathway and is implicated in the tumor growth and metastasis of OSCC." (PMID 32641093, 2020). "In various human malignancies, aberrant activation of the STAT3 signaling pathway is closely associated with tumor EMT, invasion and metastasis." (PMID 33330321, 2020). "Constitutive overactivation of STAT3 is known to be implicated in the pathogenesis of tumor development and progression." (PMID 33053804, 2020). "To have a better understanding of STAT3 and the tumor immune microenvironment, we analyzed the association between STAT3 mRNA expression level and tumor purity using the TIMER database." (PMID 32486001, 2020). "DNMT1 and p-STAT3 (downstream factors of RCC2) are implicated in therapeutic resistance in GBM tumor cells by functioning in an epistatic manner with RCC2." (PMID 33521058, 2020). "Studies have shown that tumor-associated B cells and activated STAT3 can promote tumor progression through regulating angiogenesis." (PMID 32624696, 2020). "It is thought that most tumor-associated astrocytes are likely to be of the A2 subtype, which highly expresses the phosphorylated (activated) form of the signal transducer and activator of transcription-3 (p-STAT3) pathway." (PMID 32751846, 2020). "One study has proven that tumor associated macrophages (TAMs) increase the number, tumorigenicity and drug resistance in CSCs through STAT3 activation." (PMID 33372595, 2020).